BLK (BLK proto-oncogene, Src family tyrosine kinase)
Diseases named in the same sentence as BLK in open-access papers (continued):
Sharing a sentence is not in itself a finding about the gene and the disease.
rheumatoid arthritis (14 papers, 2011 to 2025). A chronic, systemic autoimmune disorder characterized by inflammation in the synovial membranes and articular surfaces. "Epistasis between BANK1 rs3733197 and BLK rs13277113 in rheumatoid arthritis: association of BANK rs3733197 G allele and BLK rs13277113 genotypes." (PMID 23646104, 2013). "BLK has been identified as a risk factor to rheumatoid arthritis (RA) primarily in Asian or European-derived populations." (PMID 32153635, 2020). "Similarly, for the BLK locus associated with rheumatoid arthritis, SLE, and Kawasaki disease, a significant decrease in expression was observed with the eQTL rs10098664 (p = 2.7E−14) and was driven by individuals who carry an increasing dose of the alternate eQTL C allele." (PMID 30046115, 2018). "Since the discovery of BLK as a SLE susceptibility gene, SNPs in the BLK locus have also been shown to associate with disease risk in systemic sclerosis, rheumatoid arthritis, Sjögren's syndrome, and Kawasaki disease." (PMID 24637841, 2014). "Of note, the lack of clinical and laboratory information (bone erosions, rheumatoid nodules, autoantibodies such as anti-CCPs, rheumatoid factor) as well as the absence of mRNA or protein expression studies to correlate with the four BLK and BANK1 variants studied, are some limitations of our study." (PMID 32153635, 2020). "Although BLK has been reproducibly identified as a risk factor in rheumatoid arthritis (RA), reports are conflicting about the contribution of BANK1 to RA susceptibility." (PMID 23646104, 2013).
diabetes (13 papers, 2012 to 2025). "We report a patient who developed diabetes with a 1.58-Mb Chr17q12 microdeletion and BLK gene c.211G > A mutation using the cytoscan high-density array and whole-exome sequencing analysis." (PMID 32028929, 2020). "This variant is predicted to disrupt the canonical acceptor splice site, resulting in a loss-of-function allele, consistent with reports that BLK deficiency impairs β-cell function and may contribute to diabetes pathogenesis." (PMID 41153735, 2025). "It is plausible that different BLK variants may contribute not only to monogenic diabetes but also to increased susceptibility to polygenic forms." (PMID 41153735, 2025). "Borowiecet et.al., also suggested that the diabetogenic environment conferred by an increased body weight might be necessary for translation of the beta-cell abnormalities caused by the BLK gene variant into diabetes." (PMID 28095440, 2017). "We excluded the remaining MODY genes (CEL, PDX1, PAX4, BLK, KLF11, NEUROD1) from this analysis since either very few missense mutations in these genes have been associated with early onset diabetes or the genetic evidence for association is limited." (PMID 29207974, 2017). "The number of variants detected was greater than in Stage 1 since five additional monogenic diabetes genes (CEL, EIF2AK3, ABCC8, BLK, and KLF11) were sequenced." (PMID 29207974, 2017). "To date, there were no reports on NEUROD1, INS, BLK and ABCC8 variants in pregnant women with diabetes." (PMID 28095440, 2017). "However, for the PDAC patients with a diabetes history, elevated expression of BLK results in a remarkably poorer clinical outcome when compared with patients whose tumors had low expression of BLK, although the statistical results showed no significance." (PMID 38739359, 2024). "In addition, we also found a very significant upregulation of the Src kinases member BLK in PDAC patients with diabetes as compared to tumors developed by non-diabetic patients." (PMID 38739359, 2024).
Autoimmunity (6 papers, 2013 to 2025). The occurrence of an immune reaction against the organism's own cells or tissues. "Genetic risk factors have been newly identified for Sjögren’s syndrome, including IRF5, STAT4, CXCR5, IL12A, HLA-DRA, and BLK, which are linked to autoimmune disorders as well." (PMID 40136761, 2025). "Characteristics of case–control studies on BLK (rs13277113, rs2736340, rs4840568) polymorphisms and autoimmunity disease risk included in the meta-analysis." (PMID 28885337, 2017). "The B cell adaptor protein with ankyrin repeats (BANK1) and the B lymphoid tyrosine kinase (BLK) have been genetically associated with autoimmunity." (PMID 23555801, 2013). "It has been proposed that the predisposition to autoimmunity associated with low BLK expression may reflect involvement of the B cell repertoire established during B cell development." (PMID 24023612, 2013). "Together these data identify a novel function for BANK1 and BLK in repression of type I IFN and demonstrate how rare variants in SLE risk genes increase type 1 interferon activity which is central to development of autoimmunity." (PMID 31101814, 2019). "The incomplete penetrance of autoimmunity in BLK heterozygous individuals and the absence of overt autoimmunity in BlkR125W/R125W mice may be due to the differences in environmental exposure to stimulants of T1 IFN such as viral infection." (PMID 31101814, 2019).
maturity-onset diabetes (6 papers, 2013 to 2025). "BLK (rs1478898-A) was also found to be associated with decreased risk of obesity (OR = 0.97, P = 5.6×10−8) and type 2 diabetes (OR = 0.96, P = 4.5 × 10−5)." (PMID 31551469, 2019). "They reported that the p.Ala71Thr mutation substantially impaired this function, concluding that BLK represents a previously unrecognized modulator of β-cell function, whose deficiency may lead to maturity-onset diabetes of the young type 11 (MODY11)." (PMID 41153735, 2025). "In summary data-based MR analysis, it was reported that BLK gene mutation is causally associated with the onset of SLE, meanwhile, BLK gene mutation could be caused by maturity-onset diabetes of the young, including T1DM." (PMID 37195987, 2023). "The sequence variations in or near the BLK gene have been shown to cosegregate with maturity-onset diabetes of the young (MODY) in familial studies." (PMID 24023612, 2013).
Kawasaki disease (5 papers, 2013 to 2022). A rare inflammatory disease characterized by an acute febrile, systemic, self-limiting, medium-vessel vasculitis primarily affecting children. "Genotypes of the SNPs of ITPKC (inositol 1,4,5-trisphosphate 3-kinase C) and BLK (B-lymphoid tyrosine kinase), which confer susceptibility to Kawasaki disease (KD)." (PMID 30592753, 2018). "Similarly, CD40 rs4813003, BLK rs2254546, BLK rs2736340 and BLK rs2618476 were identified as susceptibility markers for Kawasaki disease, a vasculitis affecting small- and medium-sized arteries." (PMID 36233442, 2022). "The BLK and CD40 loci have been associated with Kawasaki disease (KD) in two genome-wide association studies (GWAS) conducted in a Taiwanese population of Han Chinese ancestry (Taiwanese) and in Japanese cohorts." (PMID 24023612, 2013).
Obesity (5 papers, 2014 to 2021). Accumulation of substantial excess body fat. "In the pre-HCT group we found significantly lower expression of AGTR2, BLK, FLJ32810 and TMEM133 genes, and significantly higher expression of MOV10 and WNK1 genes compared with the obesity control group." (PMID 33927307, 2021).
Sjögren's syndrome (4 papers, 2013 to 2025). "BLK was also recently identified as a susceptibility gene for multiple autoimmune phenotypic traits, including SLE, SSc, Sjögren's syndrome and RA." (PMID 23646104, 2013). "With evidence for an association of BANK1 and RA, both BANK1 and BLK should be considered pleiotropic genes involved in the genetic background of distinct autoimmune phenotypes including SLE, SSc, Sjögren's syndrome and now RA." (PMID 23646104, 2013).
bladder cancer (3 papers, 2017 to 2024). "Specifically, BLK has been associated with inducing autophagy in bladder cancer cells, thereby impeding the progression of bladder cancer." (PMID 38261733, 2024). "In the bladder cancer cells, clinopodiside A caused autophagy, which was mediated by the signaling of BLK and RasGRP2, independently." (PMID 36199691, 2022). "In the present research, clinopodiside A promoted autophagy in the bladder cancer cells by reducing BLK protein level, which supports the view that BLK favors cancer cell survival." (PMID 36199691, 2022). "In conclusion, our results suggest that clinopodiside A inhibits the growth of the bladder cancer cells via BLK- and RasGRP2-mediated autophagy." (PMID 36199691, 2022). "In conclusion, our results suggest that clinopodiside A inhibits the growth of the bladder cancer cells via the induction of autophagy which is mediated by BLK and RasGRP2." (PMID 36199691, 2022). "For example, in the TCGA bladder cancer (BLCA) dataset, BLK and CD19 show nearly perfect marker-like co-expression, while the putative B-cell marker BLNK is largely uncorrelated with CD19." (PMID 28239471, 2017).
chronic myeloid leukemia (3 papers, 2020 to 2024). "In contrast, there is evidence that BLK can inhibit tumor progression, i.e., in a mouse model, it inhibits the progress of chronic myeloid leukemia via increasing the expression of p27." (PMID 36199691, 2022). "Although a nascent body of evidence suggests BLK may be a useful biomarker and drug target in solid human malignancies, BLK activity is context dependent and acts as a tumor suppressor in chronic myeloid leukemia." (PMID 33233470, 2020). "Dasatinib, utilized to inhibit BLK both in this study and in previous works, has been approved by the FDA for the treatment of chronic myelogenous leukemia and Philadelphia chromosome-positive acute lymphoblastic leukemia." (PMID 38177125, 2024).
leukemia (3 papers, 2021 to 2025). A malignant (clonal) hematologic disorder, involving hematopoietic stem cells and characterized by the presence of primitive or atypical myeloid or lymphoid cells in the bone marrow and the blood. "As in infant leukemia cells, BLK was the second most upregulated gene in pediatric KMT2A/MLL-R+ ALL cells showing a 4.38-fold higher expression level than in normal hematopoietic cells (P-value < 1 × 10-8)." (PMID 36627892, 2022). "Genes that have been reported as abnormally methylated in leukemia, including CPEB1, BLK, FLT3, PAX5, EBF1, HDACs, IKZF1, RB, etc., were also detected in this study." (PMID 41226303, 2025). "As expected, several previously reported genes with abnormal methylation in leukemias such as CPEB1, BLK, FLT3, ZCCHC7, EBF1, HDACs, IKZF1, RB1, CDK6, DOCK5, DPP10, MUC4, JAKs, KIT, KRAS, LINC01013, MAD1L1, NOTCH1, and STATs, among others, were also detected." (PMID 41226303, 2025).
lupus nephritis (3 papers, 2012 to 2018). Glomerulonephritis in the context of systemic lupus erythematosus. "An additional six genes showed an association with lupus nephritis with p <0.001 (PMS2, TNIP1, CARD11, ITGAM, BLK and IRAK1)." (PMID 24386384, 2013).
lymphoma (3 papers, 2015 to 2021). A malignant (clonal) proliferation of B- lymphocytes or T- lymphocytes which involves the lymph nodes, bone marrow and/or extranodal sites. "Analytical results indicated that some inferred genes, such as RAC3, TEC, IRAK2/3/4, PRKCE, SMAD3, BLK, TXK, PRKCQ, were associated with the initiation and progression of lymphoma." (PMID 34899868, 2021). "The analytical results showed that some of these genes (RAC3, TEC, IRAK2/3/4, PRKCE, SMAD3, BLK, TXK, PRKCQ) could be novel lymphoma-associated genes." (PMID 34899868, 2021). "Other inferred genes, such as BLK (ENSP00000259089), TXK (ENSP00000264316), and PRKCQ (ENSP00000263125), have also been associated with lymphoma." (PMID 34899868, 2021).
myositis (3 papers, 2018 to 2024). "Next, we colocalized IIM signals that overlapped IMD signals, and found seven potentially novel myositis associations mapped to immune-related genes, including BLK, IRF5/TNPO3, and ITK/HAVCR2, implicating a role for both B and T cells in IIM." (PMID 39044428, 2024).
T-cell lymphomas (3 papers, 2015 to 2024). "Our previous studies of novel markers for cutaneous T-cell lymphomas revealed ectopic expression of B-lymphoid tyrosine kinase (BLK) both in vitro in CTCL cell lines as well as MF lesional skin; this observation was recently confirmed in independent studies." (PMID 25957418, 2015). "Beyond DSRCT, BLK has been suggested as an oncogene in B and T-cell lymphomas." (PMID 38177125, 2024). "In contrast, the application of BLK inhibitors in treating T-cell lymphoma (where BLK was shown as an oncogene) should be used with caution because inhibiting BLK may attenuate cGAS cytosolic retention leading to deficiency in cGAS activation and dampened T-cell recruitment into tumors." (PMID 35795661, 2022).
viral infection (3 papers, 2019 to 2023). "Moreover, we evaluated the role of BLK in host defense against viral infection using an in vivo xenograft tumor model and found that BLK deficiency enhanced SVA-induced oncolysis by inhibiting cellular antiviral response and promoting SVA proliferation." (PMID 37871014, 2023). "In this study, we identified BLK as a positive modulator of IRF3-dependent antiviral signaling in response to viral infection." (PMID 37871014, 2023). "Collectively, the most valuable finding from our study is that targeting BLK offers a protective function against viral infection by enhancing IRF3 activation and IFN production." (PMID 37871014, 2023). "We next evaluated the role of BLK in host defense against viral infection based on an in vivo xenograft tumor model." (PMID 37871014, 2023). "Upon viral infection, BLK undergoes Y309 autophosphorylation and directly phosphorylates IRF3 at Y107, together with TBK1-induced IRF3 S386 and S396 phosphorylation, to achieve sufficient IRF3 activation and elicit robust downstream antiviral responses." (PMID 37871014, 2023). "This set of genes is related to receptors and immunoglobulins of B and T lymphocytes (e.g., CD3, BLK, CD79, IGHXX) involved in the dynamic regulation of the inflammatory response and the complement-mediated promotion of the humoral response to viral infection." (PMID 35743918, 2022).
dermatomyositis (2 papers, 2014 to 2015). Dermatomyositis (DM) is a type of idiopathic inflammatory myopathy characterized by evocative skin lesions and symmetrical proximal muscle weakness. "The present data highlighted the strong contribution of BLK to polymyositis/dermatomyositis susceptibility, irrespective of ethnicity." (PMID 24632671, 2014).
melanoma (2 papers, 2020 to 2022). A malignant, usually aggressive tumor composed of atypical, neoplastic melanocytes. "While the role of BLK in solid human malignancy is not as convincingly established, increased BLK activity amplifies drug resistance mechanisms in melanoma cells." (PMID 33233470, 2020).
pancreatic disease (2 papers, 2020). "Combining emerging evidence with previously published findings, we suggest a mechanism for the relationship between BLK, the PDX1 transcription factor, and pancreatic disease." (PMID 33233470, 2020). "Additionally, our data provide increased understanding of the relationship between BLK protein tyrosine kinase, PDX1 transcription factor, and pancreatic disease." (PMID 33213062, 2020).
AIDS (1 paper, 2025). A syndrome resulting from the acquired deficiency of cellular immunity caused by the human immunodeficiency virus (HIV). "Several top-ranking genes, including BLK, STAT4, and TNIP1, have been previously implicated in SjD and other AIDs, validating our approach." (PMID 40429780, 2025).
Arthritis (1 paper, 2017). Inflammation of a joint. "The first irreversible BTK kinase inhibitor PCI-32765, which has demonstrated the proof-of-concept for the anti-arthritis efficacy by direct inhibition of BTK kinase, also bears potent activities against BLK, BMX, EGFR, Her2, ITK, JAK3, TEC and others." (PMID 28352114, 2017).
emphysema (1 paper, 2021). "We identified a series of significant pathways, including BCR signaling pathway, ECM-related pathways, NF-κB and TGF-β signaling pathways, and several hub genes (i.e. CD19, BLK, MS4A1, POU2AF1, and COL6A1) that may be involved in the emphysema phenotype of COPD." (PMID 33535173, 2021).
endothelial dysfunction (1 paper, 2025). In vascular diseases, endothelial dysfunction is a systemic pathological state of the endothelium (the inner lining of blood vessels) and can be broadly defined as an imbalance between vasodilating and vasoconstricting substances produced by (or acting on) the endothelium. "Ibrutinib-specific off-targets LCK, JAK3, and FLT3 were predicted to trigger inflammation processes related to hypertension; ERBB2, BLK, SRC, and CSK were predicted to trigger oxidative stress and endothelial dysfunction; and CSK were predicted to trigger the RAAS overactivation." (PMID 40744952, 2025).
giant cell arteritis (1 paper, 2022). "In contrast, a potential influence of CD40 rs1883832 and BLK rs2736340 polymorphisms was previously reported on the development of ischemic manifestations in patients with giant cell arteritis." (PMID 36233442, 2022).
glomerulonephritis (1 paper, 2014). A renal disorder characterized by damage in the glomeruli. "Consequently, we reasoned that if BLK were a bona fide susceptibility gene, then reducing its expression would either accelerate the onset of glomerulonephritis or increase its incidence and severity in B6.lpr mice." (PMID 24637841, 2014).
Large vessel vasculitis (1 paper, 2022). A type of vasculitis (inflammation of blood vessel walls) affecting large arteries such as the aorta and branches of the aorta. "It was also the case for the potential implication of BLK rs2736340 and BANK1 rs10516487 in Takayasu arteritis, another primary large-vessel vasculitis that involves mainly young individuals." (PMID 36233442, 2022).
leprosy (1 paper, 2021). Leprosy is a chronic infectious disease affecting primarily the skin and peripheral nervous system. "Indoleamine 2,3-dioxygenase 1 (IDO1) expression alone was highly discriminatory, followed by TLR10, BLK, CD38, and SLAMF7, whereas the HS3ST2 and CD40LG mRNA separated multi- and paucibacillary leprosy." (PMID 34695167, 2021). "As for differentiating leprosy per se vs. ODD, genes IDO1, BLK (exon 11), CD38, CXCL11, and SLAMF7, all had an area under the curve (AUC) of at least 96% with their lower bound 97% confidence intervals above 90%." (PMID 34695167, 2021).
lung adenocarcinoma (1 paper, 2021). A carcinoma that arises from the lung and is characterized by the presence of malignant glandular epithelial cells. "Increased expression levels of BLK and MS4A1 have been reported in lung adenocarcinoma, and BLK and CD19 have been reported to be significantly correlated with the overall survival in patients with lung adenocarcinoma." (PMID 34943992, 2021).
mantle cell lymphoma (1 paper, 2024). Mantle cell lymphoma is a rare form of malignant non-Hodgkin lymphoma affecting B lymphocytes in the lymph nodes in a region called the ``mantle zone''. "Zanubrutinib is an inhibitor of both BLK and Bruton’s tyrosine kinase (BTK), targeting BTK for the treatment of multiple hematologic diseases such as mantle cell lymphoma (MCL)." (PMID 38997544, 2024).
nephritis (1 paper, 2022). Inflammation of renal tissue. "Accordingly, we also evaluated the potential association of CD40, BLK and BANK1 with the increased risk of nephritis or GI complications in our study." (PMID 36233442, 2022).
psoriasis (1 paper, 2020). An autoimmune condition characterized by red, well-delineated plaques with silvery scales that are usually on the extensor surfaces and scalp. "We found one crossover locus of IL13 for psoriasis, two crossover loci BLK and ITGAM/ITGAX genes for SLE and four crossover loci near TFPI, CYP2A1, PECAM1, and CXCL12 for CAD data set." (PMID 32779262, 2020).